CD46 (CD46 molecule)
Description:
Acts as a cofactor for complement factor I, a serine protease which protects autologous cells against complement-mediated injury by cleaving C3b and C4b deposited on host tissue. May be involved in the fusion of the spermatozoa with the oocyte during fertilization. Also acts as a costimulatory factor for T-cells which induces the differentiation of CD4+ into T-regulatory 1 cells. T-regulatory 1 cells suppress immune responses by secreting interleukin-10, and therefore are thought to prevent autoimmunity. (Microbial infection) A number of viral and bacterial pathogens seem to bind MCP in order to exploit its immune regulation property and directly induce an immunosuppressive phenotype in T-cells. (Microbial infection) Acts as a receptor for Adenovirus subgroup B2 and Ad3. (Microbial infection) Acts as a receptor for cultured Measles virus. (Microbial infection) Acts as a receptor for Herpesvirus 6/HHV-6. (Microbial infection) May act as a receptor for pathogenic bacteria Neisseria and Streptococcus pyogenes. (Microbial infection) Plays a minor role in fiber protein-mediated human adenovirus 55 infection; via its interaction with fiber protein. Plays a minor role in fiber protein-mediated human adenovirus 14a infection.
Synonyms: MCP; MIC10; TRA2.10; MGC26544; TLX; AHUS2
Tractability: Small molecule: a structure with a bound ligand is known. Antibody: its Gene Ontology location is reachable by antibodies, with high confidence; UniProt predicts a signal peptide or a membrane-spanning region; the Human Protein Atlas places it where antibodies can reach. PROTAC: ubiquitination databases record sites on it; its protein half-life has been measured.
Gene: Protein-coding gene on chromosome 1 (207,752,037 to 207,795,513, forward strand). Ensembl gene ENSG00000117335.
Subcellular location: Cytoplasmic vesicle, secretory vesicle, acrosome inner membrane
Subcellular location (Human Protein Atlas): Plasma membrane
Pathways (Reactome):
Immune System: Regulation of Complement cascade
Gene Ontology:
Molecular function: cadherin binding; protein binding; protein sequestering activity; signaling receptor activity
Biological process: positive regulation of interleukin-10 production; positive regulation of memory T cell differentiation; positive regulation of regulatory T cell differentiation; positive regulation of T cell proliferation; positive regulation of transforming growth factor beta production; regulation of Notch signaling pathway; T cell mediated immunity; adaptive immune response; negative regulation of complement activation, classical pathway; regulation of immune response
Cellular component: cell surface; extracellular exosome; focal adhesion; plasma membrane; inner acrosomal membrane; membrane
Genetic constraint (gnomAD): Loss-of-function variants: 13 observed, 27.09 expected, observed/expected ratio (o/e) 0.48, 90% interval 0.31 to 0.76. The upper end of that interval is the gene's LOEUF score, 0.76, which puts it in group 3 of 6, group 1 being the genes least tolerant of losing a copy. Missense variants: 282 observed, 319.14 expected, observed/expected ratio (o/e) 0.88, 90% interval 0.8 to 0.98. Synonymous variants: 101 observed, 112.84 expected, observed/expected ratio (o/e) 0.9, 90% interval 0.76 to 1.06.
Gene-disease validity (ClinGen):
ClinGen rates the evidence that CD46 causes each of these diseases.
atypical hemolytic-uremic syndrome (semidominant): Definitive. A rare, genetic thrombotic microangiopathy due to dysregulation of the alternative complement pathway and characterized by the triad of hemolytic anemia, thrombocytopenia, and acute renal dysfunction.
Homologues: Orthologues: chimpanzee CD46 (87% identical), macaque CD46 (83% identical), guinea pig Cd46 (49% identical), mouse Cd46 (46% identical), pig CD46 (42% identical), rat Cd46l1 (38% identical). Paralogues in human: CR1 (26% identical), C4BPA (25% identical), CR1L (24% identical), CSMD2 (24% identical), CSMD3 (24% identical), CR2 (23% identical), SVEP1 (22% identical), CSMD1 (21% identical), CD55 (19% identical), SEZ6L (19% identical), SEZ6 (18% identical), SEZ6L2 (17% identical), and 27 more.
Diseases named in the same sentence as CD46 in open-access papers:
CD46 is named in the same sentence as 199 diseases in open-access papers, as found by Europe PMC text mining. Sharing a sentence is not in itself a finding about the gene and the disease. The quoted sentences say what the papers report.
viral infection (35 papers, 2011 to 2026). "Human CD46 causes the suppression of immune responses caused by viral infection, and facilitates viral dissemination into the CNS, leading to glial activation and T cell infiltration." (PMID 34408631, 2021). "Bovine CD46 was identified as the receptor for BVDV after monoclonal antibodies directed against the receptor inhibit viral infection." (PMID 38041163, 2023). "To date, bovine CD46 is the only identified BVDV receptor and monoclonal antibodies against CD46 block virus infection." (PMID 34204224, 2021). "Again, virus infection in cells expressing human CD46 was observed with Stealth-A09 whereas that of an isogenic and untargeted MeV-Stealth (no scFv) or Stealth-K1/N1E was negligible." (PMID 33534834, 2021). "The cell vulnerability to virus infection and syncytia formation has been shown to correlate with the level of CD46 expression." (PMID 33291506, 2020). "This indicates that additional cellular factors are required for successful virus infection after binding to CD46." (PMID 31963539, 2020). "Using the CMV infectivity assay, anti-CD46 mAb 2E7 limited virus infection using TB40/E wt in a concentration dependent manner with a maximum inhibition of ~50%." (PMID 31221976, 2019). "There was a significant reduction in infected cells for both strains in all three CD46-KO populations in comparison to wt, supporting findings with siRNA-treated cells that modulating levels of CD46 negatively impacted virus infection." (PMID 31221976, 2019). "In contrast, nestin+ cells were maintained at all dpi in CD46+ mice in comparison to mock-infected mice, suggesting that IFNγ preserves this population during a CNS viral infection." (PMID 27178303, 2016). "A potential viral receptor can either be ubiquitously expressed on the host cell surface (like CD46) or can be transported to the surface immediately upon virus infection." (PMID 25470779, 2014). "But we observed down-regulation of cell surface CD46 expression in these cells during the first 3 days of virus infection." (PMID 25470779, 2014). "Under abortive viral infection in HeLa cells, we observed initial decrease in cell surface CD46 as well as GP96 expression, which later returned back to basal level by 3–4 days post infection (dpi)." (PMID 25470779, 2014). "Notably, increased expression of complement regulatory proteins (e.g. CD35, CD55, CD46, and CD69) on neutrophils and monocytes has been associated with bacterial and viral infections." (PMID 40568581, 2025). "However, tumor cells with a higher CD46 expression are much more vulnerable to virus infection along with the formation of syncytia." (PMID 33291506, 2020). "All three anti-CD46 mAbs significantly reduced virus infection by both CMV strains." (PMID 31221976, 2019). "Also as expected, anti-CD46 antibodies limited virus infection in both the epithelial cells and trophoblasts." (PMID 31221976, 2019). "However, clones 1A11, 3F8 and 5F6 did not inhibit binding to CD46, despite their stronger affinity for Ad11 particles, suggesting that these antibodies may inhibit viral infection through a mechanism other than blocking the binding of CD46 to the virus." (PMID 40561062, 2025). "However, CD46 expression was marginally down regulated during the first 2 days of viral infection." (PMID 25470779, 2014). "The results suggested that CD46 is involved in CSFV infection, since blockade of the protein results in an almost complete inhibition of viral infection." (PMID 38041163, 2023). "Additionally, we examined whether knocking down CD46 with siRNA impacted virus infection." (PMID 31221976, 2019). "Our results suggest that productive viral infection is dependent on a delicate balance between cell surface GP96 expression and several other receptors including CD46." (PMID 25470779, 2014).
viral infection (continued). "It remains unclear whether HAdV-7 relies on both CD46 and desmoglein-2 (DSG2), whether these receptors act synergistically or independently, and how their interactions influence viral infection dynamics." (PMID 41989164, 2026). "Experiments examining viral infection of the mouse LL/2 cell line expressing human CD46 support that ICVB-1042 does not replicate upon entering non-human cells These findings are consistent with previous observations that group B Ad fibers bind CD4612,34." (PMID 39271928, 2024). "We also show that IL22 reduces the expression of viral entry receptors (e.g. ACE2, TMPRSS2, DPP4, CD46 and TNFRSF14), increases the expression of anti-viral proteins (e.g. RSAD2, AOS, ISG20 and Mx1) and, consequently, reduces the viral infection of neighboring cells." (PMID 34045640, 2021). "The interaction of CD46 with one or several known entry factors (e.g., PDFGRα, Nrp2, CD147, and/or OR14I1) or yet to be identified factors may be required for virus infection by mediating viral endocytosis or viral fusion with the endosomal membrane." (PMID 31221976, 2019). "CD46 (MCP) is a ubiquitously expressed human type I transmembrane glycoprotein that was originally discovered as a complement regulatory protein and then a cell-entry receptor enabling viral infection." (PMID 25309874, 2014). "Although these cell lines did not express the known primary cellular receptors for Ad11p virus infection (i.e., CD46), Ad11pE1GFP could infect and express GFP with various efficacies." (PMID 34777270, 2021). "Taken together, we here established CD46 knock-out RPTEC/TERT1 cell line that will be useful in understanding and dissecting the role of RPTECs and the complement in host-pathogen interactions including viral infections or enterobacterial infections including EHEC." (PMID 30958843, 2019). "Further, we demonstrate a CD46-dependent entry pathway of virus infection in trophoblasts, but not in fibroblasts, highlighting the complexity of CMV entry and identifying CD46 as an entry factor in congenital infection." (PMID 31221976, 2019).
measles (25 papers, 2011 to 2024). A highly contagious viral infection caused by the measles virus. "Actually, heterozygous rs2724384 polymorphism in CD46 gene is associated with a two-fold decrease in measles vaccine-induced antibody levels." (PMID 39421749, 2024). "For instance, variants in the interferon-induced protein 44 like (IFI44L) and the cluster of differentiation 46 (CD46) genes were associated with measles-specific neutralizing antibody titers in response to MMR vaccine." (PMID 35360730, 2022). "In this regard, single-nucleotide polymorphisms of cytokine and cytokine receptor genes and genetic variants of genes involved in MeV infection, such as CD46, have been associated with measles vaccine-induced neutralizing antibodies and T cell response." (PMID 31795157, 2019). "Animals expressing chimeric CD46, particularly transgenic mice, have been shown to be susceptible to other viruses that use CD46, including human herpesvirus 6 and measles, but require modifications that complicate studying vaccines and immunogenicity." (PMID 27846256, 2016). "A replicated CD46 polymorphism (rs2724384) also demonstrated associations with measles-specific IL-6 (p = 0.02), IFN-α (p = 0.007), and TNF-α (p = 0.0007) responses." (PMID 22241978, 2011). "Common CD46 polymorphisms are also associated with immune-related phenotypes such as febrile seizures following virus vaccination, neutralizing antibody responses to measles vaccine, and blood monocyte counts." (PMID 34831317, 2021). "Furthermore, a GWAS on neutralizing antibody response to measles vaccine had identified two intronic CD46 variants (rs2724384, rs2724374)." (PMID 32843070, 2020). "Breast carcinomas express abundantly cell surface CD46 and nectin-4, both utilized as cell entry receptors by the vaccine strain of measles, particularly viruses of the Edmonston vaccine lineage." (PMID 39339989, 2024). "CD46, which is ubiquitously expressed on all nucleated cells and is known to be overexpressed on various tumor entities, is the main route by which measles vaccine viruses can enter and therefore infect cells." (PMID 38339240, 2024). "Met-5A expressed significantly lower level of CD46, the cellular receptor of measles, than most mesothelioma cells." (PMID 36765886, 2023). "Genome-wide associations of CD46 and IFI44L genetic variants with neutralizing antibody response to measles vaccine." (PMID 35360730, 2022). "We here generated MeV-Stealth: a MeV Moraten vaccine strain pseudotyped with CD46-retargeted CDV that can achieve oncolysis in the presence of human measles-immune serum." (PMID 33534834, 2021). "For example, HLA class I and HLA class II genotypes and SNPs in cytokine/cytokine receptor genes (IL12B, IL12RB1, IL2, IL10) and the cell surface measles virus receptor the CD46 gene, have been reported to affect measles vaccine-induced immunity." (PMID 34683414, 2021). "The model commonly used for testing of recombinant measles vaccines are IFNAR−/−-CD46Ge mice, which express the measles vaccine strain receptor CD46 but are deficient in the type I interferon receptor." (PMID 32098134, 2020). "As target cells, we employed MC38-hCD46 cells (MC38 cells transduced to express the MeVac receptor CD46), which are infected by measles vaccine strains." (PMID 32098134, 2020). "Receptors can be widely available, such as in paramyxovirus (CD46 in measles and sialic acid in Sendai virus) and picornavirus infections (ICAM-1 in Coxsackie virus), or narrowly restricted in adenovirus infections (integrin on monocytes)." (PMID 30871070, 2019). "Given the intracavitary nature of the disease and high expression of CD46, measles therapy remains an interesting and promising approach." (PMID 28968974, 2017). "Immune modulation by CD46 signaling is best studied in response to measles vaccine strains, where ligation of CD46 inhibits T cell activation and induces regulatory T cells." (PMID 21490803, 2011).
measles (continued). "Individual genetic variants in the CD46 (rs11118580 and rs2724384) and SLAM (rs164288) genes that appear to modulate antibody responses to measles vaccine were also identified." (PMID 22241978, 2011). "For example, measles infection requires interaction with cellular receptor CD46; SNPs in CD46 genes might therefore influence the immune response to measles vaccine." (PMID 39421749, 2024). "A case of vaccine-induced measles (case 18) was particularly significant and important because, in theory, the virus could use CD46, CD150, and nectin-4 as cellular receptors." (PMID 29743202, 2018). "Thus, to study measles and vesicular stomatitis virus pseudotyped with measles entry proteins, we and others have used a modified mouse model expressing the human measles Edmonton strain receptor complement regulatory protein (CD46)." (PMID 36457491, 2022). "Signalling lymphocyte activation molecule (SLAM) has been identified as an immune cell receptor for the morbilliviruses, measles (MV), canine distemper (CDV), rinderpest and peste des petits ruminants (PPRV) viruses, while CD46 is a receptor for vaccine strains of MV." (PMID 25171206, 2014). "In B95m cells, a marmoset B-cell line widely used for the isolation of measles virus isolates, the lack of the SCR1 domain of CD46 greatly reduced Stealth-A09 infection." (PMID 33534834, 2021).
breast carcinoma (22 papers, 2005 to 2025). "High CD46 expression is an unfavorable prognostic factor associated with lower relapse-free survival in breast cancer." (PMID 40370471, 2025). "Similar findings have been reported in other studies of gynecological tumors, in which CD46 expression was related to poor prognosis in ovarian and breast cancer patients and served as an independent risk factor for survival." (PMID 38919630, 2024). "Further, clinical and experimental data in ovarian and breast cancer as well as multiple myeloma support an association between increased CD46 expression and malignant transformation and metastasizing potential." (PMID 33147799, 2020). "CD46 expression is elevated in medulloblastoma, while CD46 expression has been linked with poor prognosis in breast cancer." (PMID 27203670, 2016). "A study demonstrates that breast cancers manifest CD46 expression and that it is linked to a less favorable prognosis." (PMID 27203670, 2016). "For example, exosomes derived from the SK-Mel-28 breast cancer cell line, which express CD46 (an inhibitory complement receptor), have been shown to penetrate an in vitro human BBB model (hCMEC/D3)." (PMID 40806198, 2025). "Consistent with our findings, higher expression of CD46 has been observed in ovarian cancer, breast cancer, prostate cancer, bladder cancer, and colon cancer tissue vs. adjacent normal tissues, and the levels of sCD46 have also been reported to be increased." (PMID 38919630, 2024). "CCND1, SKIL and CD46 primarily involved in early breast cancer progression and immune evasion were predicted to be dysregulated by circRNA‐miRNA interaction." (PMID 33544410, 2021). "CD46 is reported to predict unfavorable prognosis in ovarian cancer and breast cancer as it belongs to type I membrane protein, and therefore, it can provide cell protection against autologous complement." (PMID 33160404, 2020). "Similar findings have also been found in breast cancer cases, where CD46 expression and involvement of lymph nodes represent independent risk factors for disease-free survival, and CD46 expression was found to be linked to less favorable diagnoses." (PMID 31164885, 2019). "CD46 is also overexpressed in some human cancers, including lymphomas, breast cancers, ovarian cancers, hepatocellular carcinomas, thus protecting cancer cells from the complement system." (PMID 27203670, 2016). "Previous studies have shown that the ADIPOR1, ADORA1, BTG2 and CD46 genes differ significantly between long-term survivors of breast cancer and deceased patients, both in levels of gene expression and DNA copy numbers." (PMID 20553615, 2010). "Indeed, increased CD46 expression is a prognostic indicator in multiple common malignancies, including ovarian cancer, breast cancer and hepatocellular carcinoma." (PMID 33147799, 2020). "Elevated expression of CD46 has been observed in medulloblastomas, breast cancers, and CRCs." (PMID 27203670, 2016). "The improved infectivity of Ad5/3 chimeric fiber, which recognizes Ad3 receptors (CD46 and DSG2), was demonstrated in different cancer models, including breast cancer, glioma, esophageal adenocarcinoma, and pancreatic cancer." (PMID 38675909, 2024). "We have reported that miR-520b is downregulated in breast cancer cells relative to normal breast cells, and sensitizes breast cancer cells to complement attack via directly targeting 3′UTR of CD46." (PMID 22319632, 2012). "Recent researches about Hepatitis B X-interacting protein (HBXIP) function on the breast cancer cells has been shown that CD55, CD59, and CD46 are up-regulated through p-ERK1/2/NF-jB signaling to protect breast cancer from complement-dependent cytotoxicity." (PMID 22634835, 2012). "Our screen assessed several known CD markers and identified several novel (i.e. CD63, CD98 and CD164) and less characterised (i.e. CD46, CD107a and CD321) breast epithelial markers, of which are overexpressed in at least 5% of breast cancer samples in the COSMIC database." (PMID 34120626, 2021).